CMTM3 (CKLF like MARVEL transmembrane domain containing 3)
Diseases named in the same sentence as CMTM3 in open-access papers (continued):
Sharing a sentence is not in itself a finding about the gene and the disease.
tumor (19 papers, 2014 to 2025). "The downregulation of CMTM3 in clinical tumor tissues was associated with the methylation of a single CpG site located within the Sp1/Sp3-responsive region of the core promoter." (PMID 24586462, 2014). "By contrast, CMTM3, which is located in the same region, is silenced in carcinomas and recognized as a tumor suppressive gene." (PMID 39948411, 2025). "CMTM3 is often downregulated or completely silenced in tumor cells, which is closely related to CpG islands and methylation of its promoter." (PMID 38223763, 2024). "CMTM3 is a neoplasm inhibitory gene that inhibits the tumorigenicity of GC cells mediated by epidermal growth factor receptor (EGFR) by increasing the activity of Rab5." (PMID 38536020, 2024). "CMTM3, 4, 5 and 7 play important roles in the cell cycle, leading to cell cycle arrest, tumor growth and migration inhibition." (PMID 38223763, 2024). "CMTM3 is frequently downregulated or silenced in testicular cancer cell lines and tumor tissues but highly expressed in normal testis tissues." (PMID 38223763, 2024). "Among these chemokine-like genes, CMTM3 is located in a cluster on chromosome 16q22 and possesses tumor suppressor properties across various types of malignant tumors." (PMID 39195242, 2024). "Previous studies have shown that CMTM3 can affect the efficacy of tumor immunotherapy by affecting the tumor microenvironment." (PMID 36245970, 2022). "Taken together, we evaluated the role of CMTM3 as a potential prognostic indicator and its role in regulating tumor immunotherapy by affecting the tumor microenvironment." (PMID 36245970, 2022). "Our findings demonstrate the potential mechanisms by which CMTM3 affects tumor microenvironment and cancer immunotherapy." (PMID 36245970, 2022). "CMTM3 strongly curbed the colony-forming ability of cancer cells, and this inhibited tumor cell proliferation and mediated apoptosis with caspase-3 activation via promotion of CpG methylation in cancer." (PMID 33955330, 2021). "CKLF-like MARVEL transmembrane domain-containing member 3 (CMTM3) was overexpressed in tumor tissue." (PMID 33955330, 2021). "Further, bioinformatic analysis and in vitro experiments were conducted to investigate the effect of CMTM3 on tumor cell behavior and the potential mechanism." (PMID 34475993, 2021). "Through a shRNA approach, we now focus on the tumor-suppressive contribution of endogenous CMTM3 and its mechanism." (PMID 27121055, 2016). "CMTM3 (CKLF-like MARVEL transmembrane domain containing 3) possesses tumor suppressor properties in multiple types of malignancies." (PMID 27121055, 2016). "Stable knockdown of CMTM3 promotes cell migration, invasion and tumor metastasis, increases MMP2 expression and enhances MMP2 activity." (PMID 27121055, 2016). "Several members, such as CMTM3, 5, 7 and 8, have been reported to exhibit tumour suppressor functions in many types of malignancies, including gastric, pancreatic, liver, lung, cervical, oral, ovarian and oesophageal cancers." (PMID 26474560, 2015). "Collectively, CMTM3 is frequently down-regulated in TGCT tissues, and the reduction of CMTM3 protein is associated with advanced tumor stage." (PMID 24586462, 2014). "More research is needed to explore the roles of CMTM3,5, a tumor-suppressor or promoter, in ESCA." (PMID 40179060, 2025). "In vivo, CMTM3 overexpression inhibited tumor growth in Bal-b/c nude mice." (PMID 38223763, 2024). "These contrasting findings suggest that the specific functions of CMTM3 in tumor development may be context-dependent, varying based on cancer type and the specific microenvironmental conditions." (PMID 39195242, 2024). "CMTM3 may participate in tumor immunity through a variety of mechanisms, including signaling pathways that inhibit tumor growth and promote tumorigenesis." (PMID 35252165, 2022).
tumor (continued). "The pathways by which CMTM3 may be involved were assessed using the GSEA in thirty-three tumor types from the TCGA database." (PMID 36245970, 2022). "Further research revealed that CMTM3 was directly connected to most of the immune activation genes, genes related to immune suppression status, chemokine receptor genes, and chemokine genes, and all of them are important elements of tumor microenvironment." (PMID 36245970, 2022). "Further research found that CMTM3 was positively correlated with most of the immune activation genes, genes related to immune suppression, chemokine receptor genes, and chemokine genes, which are all important components of the tumor microenvironment." (PMID 36245970, 2022). "We further analyzed the signaling pathways by which CMTM3 may be involved using GSEA in 33 tumor types from the TCGA database." (PMID 36245970, 2022). "In this study, CMTM3 expression was higher in the HCC tumor sample and in cluster 1, which means that CMTM3 might be an oncogene." (PMID 33955330, 2021). "It has been reported that CMTM3 acts as a tumor suppressor gene to inhibit numerous cancers." (PMID 34560882, 2021). "CMTM3 also has tumor suppressive functions, inhibits proliferation and migration." (PMID 34654826, 2021). "High expression of CMTM3 in prostate cancer cell also showed anti-tumor effects but the specific molecular mechanism remains unclear." (PMID 33282744, 2020). "It has been reported that CMTM3 plays crucial roles as a tumor suppressor in other human cancers." (PMID 27121055, 2016). "CMTM3 locates on 16q22.1, an important tumor suppressor locus that is involved in multiple tumors." (PMID 27121055, 2016). "However, a single CpG site located at the junction of the two Sp1/Sp3 binding sites had moderate methylation, and the methylation values were significantly inversely correlated with the expression of CMTM3 in tumor tissues." (PMID 24586462, 2014). "Human CMTM3 has been proposed as a putative tumor suppressor gene." (PMID 24586462, 2014). "The results showed that a single CpG site at −155 bp, located at the junction of the two Sp1/Sp3 binding sites, was more significantly methylated in tumor tissues (40.4% and 9.0%, respectively), in which CMTM3 was down-regulated, than in corresponding non-tumor tissues." (PMID 24586462, 2014). "It is worth mentioning that CMTM3, as an oncogene, is expressed at low levels in cancer, yet its potential promoter has high methylation levels, and aberrant promoter methylation may be an early signal of tumor development." (PMID 38223763, 2024). "CMTM3 could be a target for tumor immunotherapy and a novel immune checkpoint regulator." (PMID 36245970, 2022). "However, the regulation of CMTM3 expression and its function in tumor progression remain largely unknown." (PMID 24586462, 2014). "Our present study shows that the CpG sites near the core promoter of the CMTM3 gene are nearly devoid of methylation in TGCTs, which supports the notion that the aberrant de novo methylation of tumor suppressor genes or tumor-related genes is a rare event in TGCTs." (PMID 24586462, 2014). "In this study, CMTM3 was highly expressed in ESCA, and was closely related to the tumor stage, while CMTM5 was lowly expressed in tumor tissue." (PMID 40179060, 2025). "CKLF-like MARVEL transmembrane domain-containing 3 (CMTM3), a member of the CMTM family that is closely related to tumor occurrence and progression, plays crucial roles in the immune system, cardiovascular system, and male reproductive system." (PMID 39195242, 2024). "For example, it has been proven that CMTM3, CMTM4, CMTM5 and CMTM7 are new potential tumor suppressors, and interestingly, patients with high CMTM6 expression have a worse survival prognosis than those with low CMTM6 expression according to this study." (PMID 35983975, 2022).
tumor (continued). "Among them, CMTM3 and CMTM7 have functional characteristics of tumor suppressors, which are co-located with early endosomal marker Rab5, regulating the traffic and stability of membrane molecules, such as EGFR, VE-cadherin and BCR." (PMID 35983975, 2022). "Similarity to the CMTM3 gene, the promoter methylation of CMTM5 gene is the main mechanism of tumor evading anticancer effect." (PMID 33282744, 2020). "The tumour suppressor functions of members of the CMTM family, particularly CMTM3, 5, 7 and 8, have been extensively studied in multiple types of malignancies." (PMID 26474560, 2015). "CMTM3 can promote the degradation of EGFR to reduce its expression, activate caspase-3 to induce cell apoptosis, and partially inhibit the JAK2/STAT3 signaling pathway to suppress tumor cell proliferation." (PMID 38223763, 2024). "The expression of CKLF, CMTM1, CMTM3, and CMTM7 was correlated with cancer stage and tumor grade." (PMID 36975415, 2023). "As tumor grade increased, the mRNA expression of CKLF, CMTM1, CMTM3, and CMTM7 tended to be higher." (PMID 36975415, 2023). "These factors are not conducive to improving the effectiveness of tumor immunotherapy, suggesting that CMTM3 plays the role of an “oncogene” in most tumors." (PMID 36245970, 2022). "CMTM3 and CMTM4 genes are closely located at the tumor suppressor locus 16q22.1." (PMID 33282744, 2020). "According to the wound healing assay, treatment with the Erk1/2 inhibitor U0126 did not abrogate the tumor-promoting properties induced by knockdown of CMTM3." (PMID 27121055, 2016). "The re-expression of CMTM3 in tumor cells lacking its expression leads to the suppression of cell growth and apoptosis, which suggests that CMTM3 is a novel tumor suppressor." (PMID 24586462, 2014). "Importantly, no single case was observed where CMTM3 staining was more intense in tumor than in normal testis, further highlighting the specificity of the observed pattern." (PMID 24586462, 2014).
cancer (16 papers, 2014 to 2025). A tumor composed of atypical neoplastic, often pleomorphic cells that invade other tissues. "The CMTM3 expression is closely associated with cancer-associated fibroblasts, macrophages, myeloid dendritic cells, endothelial cells, immune activation genes, immune suppressor genes, immune checkpoints, chemokines, and related receptors." (PMID 36245970, 2022). "In this study, we supposed that CMTM3 may be a gene of Wnt signaling pathways and associated to some pathways in cancer progression along with CCND3, PPP3CA, and PPP3CC." (PMID 34475993, 2021). "CKLF-like MARVEL transmembrane domain containing 3 (CMTM3) has been reported to suppress tumors significantly in various cancer types." (PMID 40697995, 2025). "CKLF-like MARVEL transmembrane domain containing 3 (CMTM3) plays an important role in cancer development." (PMID 36782312, 2023). "Previous studies found that overexpressed CMTM3 significantly inhibited cancer cell proliferation and migration by reducing the activity of Erk1/2." (PMID 35252165, 2022). "We explore the CMTM3 expression in a variety of cancers and its correlation with the prognosis of cancer patients." (PMID 36245970, 2022). "As we mentioned, CMTM3 inhibited tumorigenesis and progression mostly in epithelial-derived cancers and few studies revealed the roles of CMTM3 in mesenchymal-derived cancers." (PMID 34560882, 2021). "CMTM3 is frequently reduced in multiple types of cancer, such as prostate cancer and renal cell carcinoma." (PMID 34560882, 2021). "By analyzing CMTM3 expression in PAN-cancer database of GEPIA, we found CMTM3 was overexpressed in most cancer types especially in PC." (PMID 34475993, 2021). "The transcriptional repression of CMTM3 in TGCTs may be mediated by the methylation of a single CpG site, even if the overall methylation of the genes is very limited, which would suggest that the underlying epigenetic mechanisms are different between TGCTs and cancer cells of somatic tissue origin." (PMID 24586462, 2014). "All of 18 (100%) cases of cancer adjacent normal tissues and normal testicular tissues had intensive or strong intensive CMTM3 expression." (PMID 24586462, 2014). "The role of CMTM3 in cancer progression remains controversial." (PMID 39195242, 2024). "The expressions of CMTM3 in cancers in the TCGA dataset were evaluated." (PMID 36245970, 2022). "The current research investigated the function of CMTM3 in various cancer types." (PMID 36245970, 2022). "We evaluated the CMTM3 expression and its prognostic value in various types of cancers." (PMID 36245970, 2022). "Overexpression of CMTM3 could inhibit the proliferation, migration, and invasion for several cancers." (PMID 35619698, 2022). "This research will shed light on the functional significance of CMTM3 in cancer." (PMID 36245970, 2022). "Our data reveal that CMTM3 might be used as a cancer biomarker." (PMID 36245970, 2022). "All of these results indicated that CMTM3 may serve different role for different cancers." (PMID 35619698, 2022). "However, the molecular biological functions of CMTM3 outside of cancer remain largely unknown." (PMID 40697995, 2025). "The mRNA expression of CKLF, CMTM1, CMTM3, CMTM4, and CMTM7 was correlated with the cancer stage, revealing that patients with more advanced cancer stages tended to have higher mRNA expression of the CMTM family." (PMID 36975415, 2023). "CMTM3, CMTM4, and CMTM5 are thought to bring about favorable prognostic factors in several cancer types." (PMID 35252165, 2022). "In KEGG analysis, CMTM3 was found to be mainly enriched in “Hedgehog signaling pathway, Wnt signaling pathway, ECM-receptor interaction and pathways in cancer”." (PMID 34475993, 2021). "We found that the re-expression of CMTM3 strongly impaired NCCIT cell motility and suppressed colony formation, which was consistent with previous reports in other cancers." (PMID 24586462, 2014).
cancer (continued). "Previous studies showed that CMTM family genes CMTM3 and CMTM5 are silenced or down-regulated by promoter CpG methylation in several carcinoma cell lines and primary tumors." (PMID 24586462, 2014). "CMTM3 was found to closely relate to cell proliferation and differentiation, Hedgehog signaling pathway, Wnt signaling pathway, ECM-receptor interaction, and pathways in cancer." (PMID 35252165, 2022). "However, CMTM3 was highly expressed in normal tissues rather than cancer tissue in KICH and UCEC." (PMID 36245970, 2022).
infection (3 papers, 2008 to 2024). The state of being infected such as from the introduction of a foreign agent such as serum, vaccine, antigenic substance or organism. "pylori strain 26,695 infection increased the expression of CMTM3 in GES-1 and AGS cells." (PMID 36782312, 2023). "CMTM3 interacts specifically with NEMO and mediates ubiquitylation and degradation of NEMO in response to infection." (PMID 36782312, 2023).
CMTM3 also shares sentences with these, for which no sentence is quoted: liver cancer (2 papers); benign prostate hyperplasia (1); bladder tumor (1); breast carcinoma (1); cervical cancer (1); endometrial cancer (1); Helicobacter pylori (1); hereditary colorectal cancers (1); inflammation (1); lung carcinoma (1); Lynch syndrome (1); sex development disorders (1); stomach cancer (1); thyroid cancer (1).